INS (insulin)
Diseases named in the same sentence as INS in open-access papers (continued):
Sharing a sentence is not in itself a finding about the gene and the disease.
type 2 diabetes (continued). "The second hypothesis concerns the defect in insulin secretion, which is well reported in type 2 diabetes." (PMID 35163806, 2022). "Our findings indicate that SZ-A, as a new type 2 diabetes therapy, promotes insulin secretion and provides more protection of β cells by preventing dedifferentiation in vivo and in vitro, and also prevents apoptosis in high glucose and palmitic acid treated insulinoma cell line." (PMID 35308210, 2022). "Besides, it is also possible that there is irisin resistance in PCOS, similar to the insulin and leptin resistance observed in obesity and type 2 diabetes (T2DM)." (PMID 35040046, 2022). "The milder GBS symptoms observed in metformin-treated, compared to insulin/sulphonylurea-treated GBS patients with type 2 diabetes, indicates that pharmacological reversal of AMPK signaling block might be associated with reduced GBS severity." (PMID 36139470, 2022). "Early introduction of insulin in type 2 diabetes has yet to show conclusive benefit in comparison with other glucose-lowering therapies, whereas both the blood pressure control arm of UKPDS and the Steno-2 study showed unequivocal evidence of ‘patient outcomes that matter’ within the trial period." (PMID 35275238, 2022). "What is unclear is whether lower insulin clearance is also important in the pathogenesis of type 2 diabetes." (PMID 35163746, 2022). "This is in agreement with earlier studies showing that type 2 diabetes in non-obese individuals has a stronger association with insulin secretion defects rather than insulin action defects." (PMID 36247141, 2022). "A hypothesis has been proposed that high apelin levels in people with type 2 diabetes might be a compensatory mechanism for decreased insulin sensitivity." (PMID 35610700, 2022). "People with Type 1 diabetes, and many with late-stage Type 2 diabetes, use rapid acting insulin analogues to control circulating glucose levels in the postprandial phase (e.g. insulin lispro or KP insulin; Humalog®, Eli Lilly & Co.)and the basal phase (e.g. insulin glargine; Lantus®, Sanofi)." (PMID 35832429, 2022). "Insufficient secretion of insulin from pancreatic β cells and poor sensitivity to insulin from multiple tissues are important for the development of type 2 diabetes (T2D) that, in turn, is often followed by late complications, disability, increased mortality, and increased health care costs." (PMID 36198307, 2022). "Protein tyrosine phosphatase 1B (PTP1B) served as a negative regulator of insulin through the dephosphorylation of the activated insulin receptor, which could be an effective target for the therapy of type 2 diabetes." (PMID 35408574, 2022). "Furthermore, metabolically healthy obese individuals with high fasting NEFA levels are less likely to develop type 2 diabetes than their insulin-resistant counterparts." (PMID 36050800, 2022). "Recognizably, PPAR activation in patients with type 2 diabetes enhances insulin and glucose levels." (PMID 36064382, 2022). "However, some studies have shown type 2 diabetic patients under insulin treatment experience internal and external struggles, and resist dealing with negative emotions." (PMID 36292529, 2022). "This is not too surprising given that type 1 diabetes is characterized by a reduced presence of insulin; while insulin can be increased in models of type 2 diabetes including those reported here, this effect typically is counterbalanced by a reduced insulin sensitivity." (PMID 36003651, 2022). "Type 2 diabetes (T2D) is characterized by a decreased insulin sensitivity." (PMID 36093068, 2022). "Like iatrogenic hyperinsulinemia, the higher post-load insulin response in patients with type 2 diabetes may lead to insulin-induced metabolic stress in the heart (metabolic cardiomyopathy), followed by increased risk of cardiac failure and arrhythmias." (PMID 35090539, 2022). "Type 2 diabetes is related to insulin resistance, although the level of insulin is high." (PMID 35890680, 2022).
type 2 diabetes (continued). "Previous epidemiological studies indicated that insulin promotes higher rates of some cancer types presentation in patients with type 2 diabetes mellitus (T2DM), such as colorectal cancer, lung cancer, breast cancer, pancreatic cancer, liver cancer, bladder cancer and neuroendocrine tumors." (PMID 35933633, 2022). "It has been documented that body weight reduction is a crucial way suggested for type 2 diabetes and NAFLD patients since weight loss could decrease hepatic triglyceride accumulation with an improvement of insulin sensitivity." (PMID 36432581, 2022). "Given that erastin could trigger ferroptosis in murine pancreatic β cells and worsen insulin secretion by pancreatic β cells in type 2 diabetes, we then investigated whether erastin is cytotoxic to normal human pancreatic cells." (PMID 35915609, 2022). "Thus we aimed to compare effectiveness of insulin degludec/liraglutide (IDegLira) versus intensified conventional insulin therapy (ICT) for type 2 diabetes in a real-world setting." (PMID 36104712, 2022). "Changes in HbA1c, plasma glucose and serum insulin in prediabetes and type 2 diabetes." (PMID 36267570, 2022). "According to the results of the Wisconsin Epidemiologic Study of Diabetic Retinopathy, in a ten-year perspective, DME will occur in 20.1% of patients with type I diabetes and 25.4% and 13.9% of patients with insulin-dependent and insulin-independent type II diabetes, respectively." (PMID 36012690, 2022). "Furthermore, OGT loss caused hyperproinsulinemia, because of a failure of proinsulin-to-insulin processing, resulting in hyperglycemia and the appearance of the same defects in islets that are found in patients with type 2 diabetes." (PMID 35527999, 2022). "Meanwhile, chronic mTORC1-S6K1 hyperactivation induced by obesity and overnutrition may attenuate insulin and mTORC2 signaling, resulting in decreased β-cell function and type 2 diabetes (T2D) development." (PMID 36299884, 2022). "I study insulin initiation among individuals with type 2 diabetes and examine whether a reform increasing the co-payment of non-insulin antidiabetics in Finland in 2017 had an inequitable effect on the initiation." (PMID 36033350, 2022). "Similarly, apoptotic bodies were shown to functionally modulate liver macrophage homeostasis to counteract Type 2 diabetes, improving glucose tolerance and insulin sensitivity." (PMID 35373929, 2022). "Moreover, in rats with type 2 diabetes, chronic oral administration of butanol fraction for 28 days significantly decreased blood glucose, increased plasma insulin, pancreatic insulin stored, liver glycogen, and improved lipid profile." (PMID 36557218, 2022). "As other pathogeneses, increased insulin clearance, decreased pancreatic β-cell function, and enlarged fat cells have been reported in the cause of non-obese type 2 diabetes." (PMID 35884949, 2022). "Interestingly, therapeutic management of periodontitis reduces systemic inflammation markers and ameliorates insulin sensitivity in type 2 diabetic patients." (PMID 35327570, 2022). "Current treatment includes insulin therapy in Type 1 diabetes and single or multiple combinations of sulfanylurea, diazolidediones, biguanides, alpha glucosidase inhibitors, meglitinides and insulin in Type 2 diabetes." (PMID 35729613, 2022). "Furthermore, oxidative stress is known to disrupt insulin sensitivity in type 2 diabetes and insulin production in type 1 diabetes." (PMID 35538231, 2022). "It was also found that lupanine potentiates the release of insulin by glucose, becoming a tool in the treatment of type II diabetes, and that sparteine (alkaloid present in small amounts in lupine, which can be easily obtained from lupanine) has the ability to be anticonvulsant." (PMID 36500649, 2022). "In addition, some studies have found that the macular thickness of patients with type 2 diabetes treated with insulin was higher than that of people in the control group." (PMID 36203780, 2022).
type 2 diabetes (continued). "Continuous subcutaneous insulin infusion (CSII) for the treatment of type 2 diabetes (T2D) can improve the structure and strength of femur of rats, but the effect of CSII treatment on the lumbar spine of T2D rats is unknown." (PMID 35637472, 2022). "People affected by this stage of the disease are likely to inject artificial insulin and may have insulin-resistant conditions in their life history that often lead to type 2 diabetes." (PMID 35056163, 2022). "For the most part, Type 2 Diabetes (T2D) attracts the most attention since it affects a huge percentage of the world’s populous because to insulin resistance in adipose tissue, muscle and liver due to decreased insulin production from pancreatic β-cells." (PMID 35407153, 2022). "Around 90% of diabetics, however, have type 2 diabetes, which is connected at the onset not with a deficiency of insulin but with a decreasing responsiveness of all cells of the body to insulin." (PMID 35216316, 2022). "Our results support the long-standing hypothesis that larger fat cells are less sensitive to insulin than smaller ones, a finding that has important implications for the battle against type 2 diabetes." (PMID 35313696, 2022). "We found no causal effect of sleep duration on fracture, type 2 diabetes, atrial fibrillation, fasting glucose, fasting insulin, or HbA1c." (PMID 36277903, 2022). "Nonetheless, higher BMI at T1D onset and the observation that pre-diabetic children are heavier and more insulin resistant than their peers may imply convergence of type 1 and type 2 diabetes phenotypes." (PMID 35784568, 2022). "Similarly, a previous study showed the smaller mitochondrial size and decreased electron transport chain activity in the muscle mitochondrial fractions of insulin‐resistant rodent models and patients with obesity and type 2 diabetes." (PMID 36117307, 2022). "While data are available that indicate that the insulin-positive cell mass is lower in the pancreas of deceased T2D people when compared to controls, the impact of decreased beta cell mass in type 2 diabetes remains debated, and more work needs to be done on that topic." (PMID 35326375, 2022). "In addition to novel shared SNPs, we further highlight one single-trait-driven SNP of interest, rs72753599, located near PROX1, a gene known to alter beta cell insulin secretion, which was shared by type 2 diabetes, T2DMadjBMI, FGadjBMI and PCOS." (PMID 35771237, 2022). "Furthermore, aggregating neuroendocrine tumours in different sites, we observed a strong excess for people with type 2 diabetes treated with insulin, albeit with the limitation of the relatively small number of patients." (PMID 35681699, 2022). "One explanation for this finding is that islet GLUT6 confers a restraining effect on insulin secretion at hyperglycemic concentrations of glucose, which are not present in the ob/ob model, but may be relevant during obese type 2 diabetes." (PMID 36077188, 2022). "Consistently, inhibiting lipolysis with acipimox restores the suppression of gluconeogenesis in response to insulin without affecting adipokines or adiponectin in subjects at risk of type 2 diabetes." (PMID 36009446, 2022). "The presence of nonesterified fatty acids (NEFAs) released from adipose tissue in obese patients may raise concerns of insulin resistance and β-cell dysfunction that leads to type 2 diabetes." (PMID 36005629, 2022). "In addition, insulin alone is inadequate to reverse all the adverse effects of type 2 diabetes (T2DM) on implant osseointegration." (PMID 35730406, 2022). "Impaired GLUT4 intracellular trafficking may underly defective muscle insulin‐stimulated glucose transport and hypothesised that levels of key proteins involved in intracellular GLUT4 trafficking are altered in type 2 diabetes." (PMID 35964329, 2022). "Thus, consistent elevation of glucose-independent insulin secretion suggests that HFD supplementation for 84 days provokes type II diabetes." (PMID 35453415, 2022).
type 2 diabetes (continued). "Increased pancreatic insulin production correlates with type 2 diabetes and obesity." (PMID 36244663, 2022). "In addition, the relation between protein-enriched diet and insulin sensitivity in type 2 diabetes remains obscure." (PMID 34059720, 2021). "This is in line with a recent report showing improved glucose control in patients with type 2 diabetes with use of pens for insulin injections, although frequent medical visits and supply of blood glucose strips could also be responsible for this improvement." (PMID 33905628, 2021). "Also, exercise training significantly decreased LDL, VLDL, TG, and cholesterol and promoted HDL and insulin sensitivity in streptozotocin–nicotinamide-induced type 2 diabetic rats." (PMID 34837961, 2021). "Recently, Zhang synthesized self-assembled micelles via the conjugation of plant-derived polymer polygalacturonic acid (PGA) and natural insulin sensitizer oleanolic acid (OA) which exhibited as an oral nano-carrier for the treatment of diabetes mellitus type II." (PMID 35223819, 2021). "In 1998 the fetal insulin hypothesis proposed that lower birthweight and adult-onset type 2 diabetes are two phenotypes of the same genotype." (PMID 33569631, 2021). "Therefore, leptin and insulin affect each other in the production mechanism, and their interaction participates in the genesis and development of many diseases such as type 2 diabetes." (PMID 33833859, 2021). "As examples, S. thunbergii decreased obesity, serum insulin, triglycerides and cholesterol in high-fat-diet-fed mice and S. polycystum decreased damage to the liver in high-sugar, high-fat diet + streptozotocin-induced type 2 diabetic rats." (PMID 34064139, 2021). "Analogs of incretin hormones have been developed to improve insulin signaling in Type 2 diabetes." (PMID 34055854, 2021). "Plasma insulin was also increased threefold, which, in combination with hyperglycaemia, would suggest that these mice may have type II diabetes, although glucose tolerance testing is required to confirm." (PMID 33687595, 2021). "Therefore, various drugs with different action mechanisms are used in type 2 diabetes such as promoting insulin production or inhibiting sugar catalysis." (PMID 35011338, 2021). "It is also noticeable that some enriched pathways in liver were correlated with islet function and diabetic progression, such as insulin secretion, type I and type II diabetes, maturity onset diabetes of the young, and AGE-RAGE signaling pathway in diabetic complications (marked in red)." (PMID 33817571, 2021). "In case the resulting β cell-like cells are capable of glucose-regulated insulin secretion, this transdifferentiation strategy might be applicable to PDAC patients with a long-term history of type 2 diabetes and insulin deficiency." (PMID 34771704, 2021). "Therefore, exploring the mechanism of electroacupuncture to lower blood sugar and improve skeletal muscle insulin sensitivity is of great significance for the treatment of type 2 diabetes." (PMID 33824679, 2021). "Impaired insulin clearance may therefore be an early sign of metabolic derangement, highlighting the need for early intervention of liver fat accumulation to obtain normalization of hepatic insulin metabolism and prevention of type 2 diabetes." (PMID 33498493, 2021). "Glucagon like peptide-1 receptor agonists (GLP-1 RAs) are commonly used to manage type 2 diabetes mellitus (T2DM) due to their ability to enhance glucose-dependent insulin secretion, reduce glucagon secretion, increase β-cell mass, delay gastric emptying and increase satiety." (PMID 33574570, 2021). "Interventions that normalize/reduce plasma insulin concentrations might play a key role in the prevention and treatment of age-related decline, obesity, type 2 diabetes, cardiovascular disease and cancer." (PMID 34360563, 2021).
type 2 diabetes (continued). "Conversely, genetically increased fasting insulin levels, but not type 2 diabetes or dyslipidemia, were causally associated with increased risk of pancreas cancer." (PMID 34681797, 2021). "In addition, some reports have shown that protein-enriched diet improves insulin sensitivity, although few reports have examined the benefit of such diet, especially its contribution to improving HbA1c in type 2 diabetes patients treated with SGLT2i." (PMID 34059720, 2021). "The first genome-wide association studies (GWAS) transformed the landscape of research into the genetics of type 2 diabetes and allowed us to test the fetal insulin hypothesis." (PMID 33569631, 2021). "Previous studies indicated that 1-kestose could raise insulin sensitivity in rats and that 1-kestose suppressed the development of glucose intolerance in type 2 diabetes rats." (PMID 34578862, 2021). "Also, insulin-induced inhibition of lipolysis has been reported in obese patients with type 2 diabetes following modulation of SNS activity." (PMID 34412646, 2021). "In this regard, the L14 extract might have therapeutic potential for type 2 diabetes by activating the insulin signaling pathways following TNF-α reduction." (PMID 33954196, 2021). "Cells become resistant to insulin in type 2 diabetes, resulting in higher demand for insulin." (PMID 34899863, 2021). "Type 2 diabetes is characterized by insufficient secretion of insulin from pancreatic β-cells." (PMID 33436850, 2021). "Interestingly, it has been reported that VDAC inhibitors can restore insulin secretion in type 2 diabetes islet donors and prevent hyperglycemia in diabetic mice." (PMID 34393781, 2021). "The accumulation of ectopic LD in human myocytes leads to a modification of lipid metabolism and consequently contributes to a reduced insulin sensitivity, a hallmark for type 2 diabetes, even in non-obese subjects." (PMID 35822042, 2021). "This cohort study assesses the occurrence of overall mortality, cardiovascular mortality, acute myocardial infarction, stroke, and hospitalization for congestive heart failure among adults with type 2 diabetes receiving long-acting insulin alone vs long- plus short-acting insulin treatment." (PMID 34559229, 2021). "In a 4-week parallel, randomized, double-blind placebo-controlled study including 81 human participants with type 2 diabetes, 10 g/day broccoli sprout powder (225 μmol sulforaphane daily) decreased fasting serum insulin and insulin resistance by 18.2 and 14.2%, respectively." (PMID 34764875, 2021). "Moreover, the Otsuka Long-Evans Tokushima Fatty (OLETF) rats were another model of obesity and type 2 diabetes used to evaluate the role of aerobic exercise on hepatic insulin sensitivity." (PMID 34203825, 2021). "In a systematic review, moderate alcohol consumption protected against type 2 diabetes and moderate amounts of alcohol may improve insulin sensitivity in previous studies." (PMID 33858402, 2021). "Moreover, pioglitazone is a potent insulin sensitiser, retards onset of type 2 diabetes by protecting beta cell function, and reduces CVD, which is a frequent comorbidity in individuals with type 2 diabetes and/or NAFLD." (PMID 33877366, 2021). "Findings from the Treatment Options for Type 2 Diabetes study and the Restoring Insulin Secretion Pediatric Medication Study illustrate the aggressive nature of T2D in youth and assert the urgent need for efficacious diabetes prevention strategies for at-risk youth." (PMID 33625364, 2021). "Insulin-deficient type 1 DM was reproduced in rats and C57BL6 mice by streptozotocin administration, whereas db/db mutant mice of the C57BLKS/J strain served as an in vivo type 2 diabetes biological platform." (PMID 34205061, 2021). "Interestingly, sEVs miRNA-mediated downregulation of STAT3 and impaired insulin signalling in skeletal muscles has been reported in type 2 diabetes." (PMID 34416903, 2021).